INS (insulin)
Diseases named in the same sentence as INS in open-access papers (continued):
Sharing a sentence is not in itself a finding about the gene and the disease.
Obesity (continued). "Obesity is closely associated with chronic inflammation, which results in whole-body impaired glucose homeostasis and insulin sensitivity." (PMID 36505236, 2022). "Adipokines are highly active biopeptides produced by adipose tissue (AT), involved in regulating glucose metabolism, insulin function and the development and progression of obesity and its associated diseases." (PMID 35872989, 2022). "Here, we show that maternal consumption of 20% (w/v) fructose water during pregnancy does not alter the metabolic balance of offspring with a chow diet, but predisposes them to obesity, fatty liver, and insulin resistance when challenged by a high-fat diet." (PMID 35479745, 2022). "Here, we report that female RAGE knockout mice are protected from high-fat diet (HFD)-induced obesity and adipose tissues-associated insulin signaling." (PMID 36348465, 2022). "In support, Treg cell specific IL-10 deficiency leads to increased insulin sensitivity and reduced obesity in male mice fed with high fat diet." (PMID 35359918, 2022). "Hormones such as leptin, which is secreted by fat cells, and insulin were found to mediate the genetic association of obesity with pre-eclampsia." (PMID 35104295, 2022). "Inflammation and decreased insulin sensitivity are linked with obesity and changes in fecal microbiota." (PMID 36532542, 2022). "Obesity is usually associated with a pro-inflammatory state, enhanced oxidative stress, which interferes with the anti-inflammatory properties of insulin." (PMID 35453376, 2022). "Adipocytes generate NEFA that affects the action of insulin and is also associated with metabolic disorders such as obesity." (PMID 36056976, 2022). "Given the known role that insulin resistance and adipose inflammation play in the development and progression of cancers, particularly obesity-associated cancers, this provides another possible link between ghrelin, insulin signaling, inflammation, and cancer." (PMID 35454071, 2022). "Previous studies have cited insulin-related disorders, including hyperinsulinemia, as one of the main causes of obesity risk and metabolic disorders." (PMID 35578225, 2022). "Four T2D subtypes were previously identified: severe insulin deficient, severe insulin resistant, mild obesity-related, and mild age-related diabetes." (PMID 36402758, 2022). "It is thought that SBH administration had the effect of improving obesity, insulin secretion, and dyslipidemia caused by an HFHCD, which was more effective than Sim administration." (PMID 35889886, 2022). "Switching of M1‐like adipose tissue macrophages (ATMs) to M2‐like ATMs, a population of macrophages associated with weight loss and insulin sensitivity, is considered a viable therapeutic strategy for obesity‐related metabolic syndrome." (PMID 35258174, 2022). "While macrophages are an important source of AT inflammation, changes in adipose T cell populations also regulate obesity-associated inflammation and insulin sensitivity." (PMID 35094654, 2022). "Zinc (Zn) deficiency is common in obesity conditions, resulting in an inflammatory status, oxidative stress, insulin resistance, and lower insulin secretion by the pancreatic β cells." (PMID 35369101, 2022). "These metabolic results suggested that female RAGE deficiency is associated with improved glucose tolerance and insulin sensitivity in HFD-induced obesity in mice." (PMID 36348465, 2022). "According to the Australian Diabetes, Obesity and Lifestyle Study, increased fruit consumption reduced the risk of developing type 2 diabetes over a 5‐year follow‐up period due to an increase in insulin sensitivity in healthy individuals." (PMID 35452190, 2022). "The abundance of species Bacteroides and Prevotella was inversely associated with obesity and improved insulin sensitivity in mice." (PMID 35990329, 2022).
Obesity (continued). "It has been shown that lean individuals at risk of developing obesity have characteristically high and/or dynamically different insulin responses to nutrients, which persist or worsen during obesity." (PMID 36580474, 2022). "It has been well documented that children with PWS are more insulin sensitive compared to BMI-matched controls or children with obesity, and it has been associated with higher levels of adiponectin in PWS." (PMID 35456360, 2022). "Obesity during childhood can cause metabolic and cardiovascular complications usually related to increased levels of insulin in the blood and its resistance and other associated complications of obesity." (PMID 36284800, 2022). "According to evidence from humans and animals, both obesity and VD deficiency seem to be strongly correlated with changes in insulin sensitivity, which can be considered the main predictor of metabolic changes." (PMID 36499033, 2022). "Lifestyle modification with weight loss can improve anovulation due to obesity and even improve insulin sensitivity in PCOS patients." (PMID 36518222, 2022). "Decreased cognitive function is associated with impaired metabolic pathways associated with obesity such as insulin signaling and leptin regulation." (PMID 35509009, 2022). "This preservation of insulin action despite obesity in Hi-ST mice was associated with differences in de novo lipogenesis and levels of C22:0 ceramide in liver and C18:0 ceramide in muscle." (PMID 36394259, 2022). "Prolonged fasting protocols have been shown to improve cardiometabolic markers associated with obesity such as insulin sensitivity, blood lipids, body weight, and abdominal circumference." (PMID 36296997, 2022). "In men, both obesity and elevated BMI are associated with decreased testosterone levels, paralleled by elevated levels of estrogen, leptin and insulin, resulting in a state of hypogonadism." (PMID 36139133, 2022). "The main problems that have been described associated with obesity are hypertension, hypercholesterolemia, increased levels of glycemia, insulin, and increased liver transaminases." (PMID 35993079, 2022). "Although the association between obesity and impaired insulin sensitivity has long been recognized, there are still subgroups of obese individuals whose insulin sensitivity is preserved." (PMID 36457708, 2022). "It is true that insulin use has been found to be associated with an increased risk of hypertension, obesity, peripheral arterial disease and several types of cancer in our previous studies." (PMID 35935880, 2022). "On the other hand, Arrb1-KO mice are susceptible to diet-induced obesity, and these mice develop increased fat mass accumulation and decreased whole-body insulin sensitivity." (PMID 35204118, 2022). "According carbohydrate-insulin model of obesity, a diet that induces insulin secretion through the anabolic effects of insulin cause weight gain and insulin resistance." (PMID 36585722, 2022). "They control hyperglycemia and prevent diabetic complications (reducing risk factors, e.g., OS and obesity) by improving insulin sensitivity, as confirmed in vivo and in humans." (PMID 36632095, 2022). "Both mRNA and serum levels of vaspin are associated with parameters of obesity and impaired insulin sensitivity." (PMID 35909571, 2022). "Several mechanisms have been proposed to explain the associations between obesity and impaired cognitive function, including inflammation, elevated leptin, insulin resistance, neuronal degradation, and impaired brain metabolism or blood flow." (PMID 35686024, 2022). "Poor insulin sensitivities have been linked with obesity, but BCAA intake/supplementation has been linked with improved insulin sensitivities, maintenance of lean body and in some cases, modest weight loss." (PMID 35382800, 2022). "Human and animal model studies have found that high levels of circulating 20-HETE are associated with obesity and MS with adverse effects on insulin signaling and IS." (PMID 36147256, 2022).
Obesity (continued). "Both neurotrophins are positively associated with obesity anthropometric measures, blood pressure, and salivary insulin." (PMID 35626286, 2022). "Obesity has also been associated with insulin and sex hormone levels as well as the insulin-like growth factor axis." (PMID 36591521, 2022). "Fasting blood glucose and fasting insulin levels in schizophrenia patients are significantly increased, and high insulin levels are high risk factors for obesity." (PMID 35690794, 2022). "Obesity can cause IR through several mechanisms, such as inhibition of carbohydrate metabolism through intracellular inhibition of insulin signaling, increased cytokines, and hormonal production by adipose tissue." (PMID 35501770, 2022). "More specifically, we estimated the level of fasting insulin (fasting insulin equivalent, FIeq) that would replicate the strength of the associations of the obesity, overweight, and elevated WC with TG/HDL and TyG." (PMID 36079745, 2022). "Adipocyte-specific CDase overexpression in obesity also reduced C16:0 and C18:0 ceramides in the liver, associated with improved hepatic insulin sensitivity and protection from diet-induced hepatic steatosis." (PMID 35789435, 2022). "In particular, HFD-induced inflammation in the hypothalamus has been extensively studied in the context of food consumption, energy expenditure, insulin and glucose homeostasis and regulates susceptibility to obesity." (PMID 35784876, 2022). "Chronic hyperinsulinemia is produced by liver-specific deletion of IDE in the existence of HFD-induced obesity, which causes a decrease in insulin clearance." (PMID 36304965, 2022). "Undoubtedly, genetic susceptibility to obesity implicates several pathways, including synaptic function, glutamate signalling, insulin secretion/action, energy metabolism, lipid biology, and adiposeness, which are all related to the central nervous system." (PMID 35677584, 2022). "Liquid carbohydrates, due to higher GI, increasing the risk of obesity; in addition, they can induce appetite, increase postprandial glucose and decrease insulin sensitivity compared to solid carbohydrates." (PMID 36159469, 2022). "Considering the metabolic role of AMP-activated protein kinase (AMPK) in insulin signalling and inflammatory pathways, it has also been proposed as a key pathogenic factor involved in obesity." (PMID 35203639, 2022). "CD4+Foxp3+ regulatory T cells (Tregs) represent a critical source of IL-10, where the loss of IL-10 Treg resulted in increased insulin sensitivity and reduced obesity in mice fed with a high-fat diet." (PMID 36362238, 2022). "Dietary fatty acids have further been associated with inflammation, obesity, insulin sensitivity, and hemostasis, and most of these have also a link to the development of dementia/cognitive decline." (PMID 35950105, 2022). "Adipose tissues normally maintain nutrient stores but an increase in adipocyte cell size causes impaired lipid levels, inflammation and insulin resistance in adipose tissue leading to progression of obesity." (PMID 36033946, 2022). "As such, obesity predisposes defective insulin signaling, lowering insulin sensitivity and trans-membranous glucose transport capacity, ultimately decreasing plasma-glucose removal." (PMID 35745174, 2022). "Mice with brain-specific PTP1B–/– deficiency showed resistance to diet-induced obesity and elevated insulin sensitivity via central modulation of leptin signal." (PMID 35607953, 2022). "Obesity is a leading risk factor for developing T2DM, and taking VKs has been previously considered to improve the insulin sensitivity associated with obesity and T2DM risk." (PMID 35495953, 2022). "FAM13A in the region on chromosome 6 associated with adult August weight has been found to modulate body fat distribution and adipocyte function in humans and mice affects adipose insulin signaling in mice and is associated with obesity also in mice." (PMID 36532132, 2022).
Obesity (continued). "Vitamin D deficiency is associated with obesity and it has been reported that Vitamin D supplementation has similar effects of exercise on glucose metabolism and insulin sensitivity in overweight and obese individuals." (PMID 35198590, 2022). "RAGE appears to be involved in the progression of obesity, associated with inflammation, reactive oxygen species (ROS) production, and insulin sensitivity." (PMID 36348465, 2022). "The study in SSA was an RCT designed to examine the mechanisms underlying the changes in insulin sensitivity and secretion in response to a 12 week exercise (combined aerobic and resistance) intervention in young Black South African women with obesity." (PMID 36166072, 2022). "Obesity is thought to be the cause of hyperinsulinemia, and the physiological mechanisms mainly involve dysregulation of lipid, insulin resistance, inflammation and adipokines imbalance." (PMID 35695553, 2022). "Mice deficient in bid were resistant to high‐fat diet‐induced obesity, hepatic steatosis and dyslipidemia with an increased insulin sensitivity." (PMID 36382356, 2022). "Women who develop GDM are often insulin-resistant, even before conception, which is often associated with maternal obesity." (PMID 35203692, 2022). "The obese, insulin-sensitive phenotype was associated with a favorable lipid profile, indicating a more metabolically healthy obesity profile." (PMID 35106505, 2022). "Low serum levels of omentin are associated with obesity, and high levels are associated with insulin sensitivity improvement." (PMID 35682868, 2022). "Recently, whole-body LRG1 loss of function has been reported to reduce obesity and improve insulin sensitivity by reduction of hepatosteatosis." (PMID 36346018, 2022). "Increased (p < 0.001) circulating concentrations of NTN-1 in obesity decreased (p < 0.05) after diet-induced weight loss being also associated with a reduction in glucose (p < 0.01) and insulin levels (p < 0.05)." (PMID 36297056, 2022). "In fact, during COVID 19 pandemic, recent studies have shown in children and adolescents an increased risk of obesity, a well-known risk factor for impaired lipid profile and increased insulin sensitivity." (PMID 35139895, 2022). "Mice with a null mutation in the laminin α4 gene exhibit resistance to obesity and enhanced insulin sensitivity." (PMID 35696439, 2022). "Results demonstrate that D3Cr muscle mass is independently associated with measures of insulin-glucose homeostasis, but obesity is a stronger predictor of insulin resistance than muscle mass." (PMID 36490255, 2022). "Visceral WAT is a crucial risk factor for obesity-associated diseases, and hypertrophic adipocytes are associated with reduced insulin sensitivity, increased inflammatory response as well as oxidative stress." (PMID 35684088, 2022). "SOCS3 expression in obesity is associated with decreased energy expenditure, increased food intake, increasing adiposity, and insulin and leptin resistance." (PMID 35406000, 2022). "Obesity causes progressive lipid accumulation and insulin resistance within muscle cells and affects skeletal muscle fibres and muscle mass that demonstrates atrophy and dysfunction." (PMID 36235772, 2022). "Obesity is often associated with elevated insulin secretion from pancreatic β cells and hyperinsulinemia effects in organs will promote increased deposition of fat in liver and adipose tissue and drive current obesity complications." (PMID 35629915, 2022). "The well-established biological functions of FGF21 as a key regulator of energy balance, glucose homeostasis, fat metabolism and insulin sensitivity provide clues as to the SLC6A19 loss-associated protection against obesity and metabolic syndrome." (PMID 35204736, 2022). "In this study of postmenopausal women, we quantified the mediating effects of leptin and CRP, fasting insulin, and estradiol in explaining the associations between obesity and ER‐positive breast, endometrial, and colorectal cancers." (PMID 35048536, 2022).
Obesity (continued). "Given its critical role in glucose metabolism, skeletal muscle has increasingly become a focus of attention in understanding the mechanisms of impaired insulin function in obesity and the associated metabolic sequelae." (PMID 35055038, 2022). "Obesity is a major risk factor for T2D, and the fasting hyperglycemia that accompanies T2D is associated with an inadequate insulin response." (PMID 36499659, 2022). "It has been reported that in humans with obesity, a moderate 5% weight loss contributes to and corresponds with improved β-cell function and improved insulin sensitivity in the adipose tissue, liver, and muscle." (PMID 35929791, 2022). "A recent study also suggests that the associations of body fat and bone parameters with insulin were clearer when FMP was used instead of BMI to classify obesity." (PMID 35684072, 2022). "Individuals with well-established risk factors for obesity have alterations in the brain’s insulin responsivity and opioid and endocannabinoid signaling that resemble those observed in obesity." (PMID 34728775, 2022). "We show that LXN-deficient mice have reduced HFD-induced obesity and improved glucose tolerance and insulin sensitivity." (PMID 35210404, 2022). "Of the various risk factors, obesity is key for type 2 diabetes to occur, as it can desensitize glucose recipient organs towards insulin action." (PMID 36670891, 2022). "Based on the primary findings for NNMT in obesity and type 2 diabetes, a recent experiment demonstrated that JBSNF-000088-treated high-fat diet-induced obesity mice exhibited weight loss, improved insulin sensitivity, and normal glucose tolerance." (PMID 35756670, 2022). "Mothers with GDM under insulin treatment are at increased risk of adverse outcomes, especially in cases of overweight or obesity." (PMID 36079820, 2022). "IR has a number of underlying causes, including obesity, stress, medication (e.g., steroids), pregnancy, insulin antibodies, and genetic defects in insulin signaling pathways." (PMID 35889789, 2022). "Further, consumption of AGEs alters β-cells function and risk factors for T1D such as insulin sensitivity and obesity." (PMID 36359899, 2022). "Although inflammation and hypertrophy of visceral WAT is predictive for the development of obesity-associated complications, Hsl knockout mice remain insulin sensitive and are even protected against diet-induced obesity." (PMID 36273647, 2022). "Of interest, NLE also positively associates with obesity, perhaps through disrupted regulation of the diurnal metabolic rhythm of insulin and glucagon." (PMID 35194360, 2022). "It is well known that obesity is highly associated with insulin sensitivity, so carbohydrate metabolism was also investigated." (PMID 35990345, 2022). "The underlying mechanisms include increased incidence of obesity and metabolic syndrome, the turbulence of glucose and insulin metabolism, and shortening of telomere length accompanied by higher DII levels." (PMID 35938119, 2022). "The major goal of the current study was to explore the function of liver RNF186 in the regulation of insulin tolerance and obesity-associated NAFLD." (PMID 35198905, 2022). "It has been demonstrated by MRI that the first weight lost in adults with obesity after lifestyle change is ectopic adiposity, and loss of hepatic lipid is the strongest predictor of improved insulin sensitivity." (PMID 35406045, 2022). "Hypothalamic loss of either insulin or leptin receptors leads to hyperphagic obesity in rodents, as does the specific disruption of leptin stimulated STAT3 phosphorylation." (PMID 36111295, 2022). "This gene is implicated in modulating diet-induced obesity, regulating insulin signaling in adipocytes, participating in Wnt signaling, and affecting the risk of certain lung diseases." (PMID 35163195, 2022). "Insulin insensitivity associated with obesity downstream of PI3K-mTOR signaling promotes lipogenesis." (PMID 35884514, 2022).